KMT2A (lysine methyltransferase 2A)
Description:
Histone methyltransferase that plays an essential role in early development and hematopoiesis. Catalytic subunit of the MLL1/MLL complex, a multiprotein complex that mediates both methylation of 'Lys-4' of histone H3 (H3K4me) complex and acetylation of 'Lys-16' of histone H4 (H4K16ac). Catalyzes methyl group transfer from S-adenosyl-L-methionine to the epsilon-amino group of 'Lys-4' of histone H3 (H3K4) via a non-processive mechanism. Part of chromatin remodeling machinery predominantly forms H3K4me1 and H3K4me2 methylation marks at active chromatin sites where transcription and DNA repair take place. Has weak methyltransferase activity by itself, and requires other component of the MLL1/MLL complex to obtain full methyltransferase activity. Has no activity toward histone H3 phosphorylated on 'Thr-3', less activity toward H3 dimethylated on 'Arg-8' or 'Lys-9', while it has higher activity toward H3 acetylated on 'Lys-9'. Binds to unmethylated CpG elements in the promoter of target genes and helps maintain them in the nonmethylated state. Required for transcriptional activation of HOXA9. Promotes PPP1R15A-induced apoptosis. Plays a critical role in the control of circadian gene expression and is essential for the transcriptional activation mediated by the CLOCK-BMAL1 heterodimer (By similarity). Establishes a permissive chromatin state for circadian transcription by mediating a rhythmic methylation of 'Lys-4' of histone H3 (H3K4me) and this histone modification directs the circadian acetylation at H3K9 and H3K14 allowing the recruitment of CLOCK-BMAL1 to chromatin (By similarity). Also has auto-methylation activity on Cys-3882 in absence of histone H3 substrate.
Synonyms: ALL1; CXXC7; HRX; HTRX; MLL; MLL1; TRX1; ALL-1; HTRX1; MLL1A; GAS7; WDSTS
Tractability: Small molecule: a drug acting on it is in phase 1 trials; a structure with a bound ligand is known; a high-quality ligand is known; it belongs to a druggable protein family. PROTAC: UniProt records ubiquitination sites on it; ubiquitination databases record sites on it; its protein half-life has been measured; a small molecule that binds it is known.
Target class: Writer; Protein methyltransferase; Epigenetic regulator
Chemical probes: MIV-6R
Gene: Protein-coding gene on chromosome 11 (118,436,456 to 118,526,832, forward strand). Ensembl gene ENSG00000118058.
Subcellular location: Nucleus; Nucleus (MLL cleavage product N320); Nucleus (MLL cleavage product C180)
Subcellular location (Human Protein Atlas): Nucleoplasm; Cytosol
Pathways (Reactome):
Circadian clock: Phosphorylated BMAL1:CLOCK (ARNTL:CLOCK) activates expression of core clock genes; Phosphorylation of CLOCK, acetylation of BMAL1 (ARNTL) at target gene promoters; The CRY:PER:kinase complex represses transactivation by the BMAL:CLOCK (ARNTL:CLOCK) complex
Gene expression (Transcription): Formation of WDR5-containing histone-modifying complexes; RUNX1 regulates genes involved in megakaryocyte differentiation and platelet function; RUNX1 regulates transcription of genes involved in differentiation of HSCs
Developmental Biology: Differentiation of naive CD4+ T cells to T helper 2 cells (Th2 cells); Transcriptional regulation of granulopoiesis
Chromatin organization: PKMTs methylate histone lysines
Immune System: Regulation of PD-L1(CD274) transcription
Gene Ontology:
Molecular function: histone H3K4 methyltransferase activity; histone H3K4 monomethyltransferase activity; histone H3K4 trimethyltransferase activity; identical protein binding; protein binding; protein homodimerization activity; protein-cysteine methyltransferase activity; unmethylated CpG binding; zinc ion binding; minor groove of adenine-thymine-rich DNA binding; chromatin binding; DNA binding
Biological process: negative regulation of DNA methylation-dependent heterochromatin formation; positive regulation of DNA-templated transcription; positive regulation of transcription by RNA polymerase II; protein-containing complex assembly; T-helper 2 cell differentiation; transcription initiation-coupled chromatin remodeling; circadian regulation of gene expression; embryonic hemopoiesis; cellular response to transforming growth factor beta stimulus; definitive hemopoiesis; epigenetic regulation of gene expression; immune system process; membrane depolarization; positive regulation of gene expression; regulation of DNA-templated transcription; response to potassium ion
Cellular component: histone methyltransferase complex; MLL1 complex; nucleoplasm; nucleus; cytosol
Genetic constraint (gnomAD): Loss-of-function variants: 13 observed, 317.04 expected, observed/expected ratio (o/e) 0.041, 90% interval 0.026 to 0.065. The synonymous counts are far from expectation, so gnomAD's model fits this gene poorly and the ratio says little. Missense variants: 3,124 observed, 4,790.7 expected, observed/expected ratio (o/e) 0.65, 90% interval 0.63 to 0.67. Synonymous variants: 1,511 observed, 1,764.8 expected, observed/expected ratio (o/e) 0.86, 90% interval 0.82 to 0.89.
Gene-disease validity (ClinGen):
ClinGen rates the evidence that KMT2A causes each of these diseases.
Wiedemann-Steiner syndrome (autosomal dominant): Definitive. Wiedemann-Steiner syndrome is a rare genetic condition characterized by distinctive facial features, hairy elbows, short stature, and intellectual disability.
Cancer hallmarks: tumour promoting inflammation (promotes); escaping programmed cell death (promotes); cell replicative immortality (promotes); proliferative signalling (promotes); invasion and metastasis (promotes); escaping immune response to cancer (promotes); angiogenesis (promotes); escaping immune response to cancer (suppresses)
Homologues: Orthologues: macaque KMT2A (99% identical), chimpanzee KMT2A (99% identical), pig KMT2A (95% identical), dog KMT2A (95% identical), rat Kmt2a (91% identical), mouse Kmt2a (91% identical), guinea pig KMT2A (68% identical), tropical clawed frog kmt2a (62% identical), Caenorhabditis elegans set-16 (7% identical), Drosophila melanogaster trr (6% identical), Drosophila melanogaster ash1 (5% identical), Drosophila melanogaster G9a (4% identical), and 14 more. Paralogues in human: KMT2B (26% identical), KMT2C (14% identical), KMT2D (14% identical), SETD1B (10% identical), SETD1A (8% identical), NSD1 (6% identical), ASH1L (5% identical), EHMT1 (5% identical), NSD2 (5% identical), NSD3 (5% identical), EHMT2 (5% identical), SETD2 (4% identical), and 7 more.
Diseases named in the same sentence as KMT2A in open-access papers:
KMT2A is named in the same sentence as 244 diseases in open-access papers, as found by Europe PMC text mining. Sharing a sentence is not in itself a finding about the gene and the disease. The quoted sentences say what the papers report.
leukemia (722 papers, 2004 to 2026). A malignant (clonal) hematologic disorder, involving hematopoietic stem cells and characterized by the presence of primitive or atypical myeloid or lymphoid cells in the bone marrow and the blood. "This demonstrates the urgent need for a better understanding of molecular mechanisms underlying the pathogenesis of KMT2A‐rearranged leukemias in order to develop more effective molecularly targeted therapeutic approaches." (PMID 39887730, 2026). "The drug combination also showed greater inhibition of cell proliferation and increased apoptosis in NPM1 mutated and KMT2A‐rearranged leukemia models with FLT3 mutations." (PMID 39887730, 2026). "Menin inhibitors represent novel drugs with astonishing clinical activity against NPM1‐mutated or KMT2A‐rearranged leukemia in patients suffering from relapsed or refractory disease." (PMID 39887730, 2026). "This myeloid conversion is frequently associated with KMT2A rearrangements and is driven by epigenetic reprogramming, impaired expression of B-cell regulators, and the presence of bipotent progenitors within leukemia or lymphoma." (PMID 42023212, 2026). "Even though being approved by the FDA as a highly effective treatment option for patients with relapsed or refractory leukemia with KMT2A‐rearrangements or NPM1‐mutations, roughly 50% of patients show no clinical response." (PMID 40181550, 2026). "In fact, many key molecular features that had been described in the context of KMT2A‐fusion proteins are highly similar to those observed in NPM1‐mutated leukemias." (PMID 39887730, 2026). "For instance, IDH-mutated gliomas exhibit selective responses to the IDH1/2 dual-target inhibitor Vorasidenib, while leukemia patients carrying KMT2A rearrangements or NPM1 mutations." (PMID 41335282, 2025). "Certain fusion genes are associated with distinct subtypes of leukemia such as KMT2A::AFF1 and KMT2A::MLLT3 (also known as MLL-AF4 and MLL-AF9, respectively)." (PMID 39858509, 2025). "The association of oncogenic KMT2A-fusion proteins with Menin and LEDGF is required for its chromatin binding, target gene expression such as the HOXA9 and MEIS1, and implicated the Menin-KMT2A interaction as a therapeutic opportunity in these leukemias." (PMID 40374809, 2025). "JNJ-75,276,617 is an effective, selective inhibitor targeting the Menin-KMT2A interaction, demonstrating efficacy in leukemia cell lines and patient samples with KMT2A-rs or NPM1 mutations." (PMID 40361241, 2025). "KMT2A plays a role in chromatin remodeling and transcriptional regulation, and its rearrangement is a hallmark of some childhood leukemias." (PMID 41462934, 2025). "Studies suggest that KMT2A-PTD alone is insufficient to cause AML and additional genetic aberrations are required for the development of KMT2A PTD-associated leukemia." (PMID 39766092, 2024). "While acute leukemias with KMT2A rearrangements occur in patients of all ages, the prognosis varies significantly among pediatric patients based on the specific leukemia subtype, age at diagnosis, and the fusion partner associated with KMT2A." (PMID 39179671, 2024). "Pediatric, adult, and therapy-related leukemias are associated with the chromosomal rearrangement at 11q23 that linked the implication of the lysine methyltransferase 2A (KMT2A) gene as a driver in AML." (PMID 39594699, 2024). "Somatic mutations and rearrangements in the KMT2A gene have been described in tumors, mainly blood malignancies, and translocations involving the KMT2A gene are common in different types of leukemia." (PMID 38397201, 2024). "Leukemia subtypes with hallmark overexpression of HOXA9 include but are not limited to those carrying KMT2A gene rearrangements (KMT2A-r), NPM1c mutations, NUP98-translocations, and EZH2 mutation." (PMID 38216972, 2024).
leukemia (continued). "Menin inhibitors hold immense promise for addressing unmet needs in various pediatric leukemia subtypes, including infant KMT2A-r ALL, high-risk KMT2A-r AML, NUP98-r AML, and others." (PMID 39179671, 2024). "Binding of DOT1L to KMT2A fusion proteins causes inappropriate H3K79 hypermethylation at KMT2A target genes, leading to an altered transcriptomic landscape that strongly favors leukemia development." (PMID 37740239, 2023). "For instance, despite normal expression of HOXA and MEIS1, perturbation of the menin-KMT2A complex impairs proliferation in leukemia cell lines of mutated CEBPα AML." (PMID 38174649, 2023). "When MEN1 and LEDGF bind to the N-terminus of KMT2A, they further activate HOXA9 and HOXA10, which are usually upregulated in leukemia with KMT2A mutation." (PMID 36824144, 2023). "Folate deficiency can cause chromosome breakage, and DNA-damaging agents have been associated with childhood-leukemia-harboring chromosome structural abnormalities (such as KMT2A gene fusion in infant leukemia, and ETV6-RUNX1 translocation)." (PMID 36831356, 2023). "KMT2A-fusion proteins generated by KMT2A-rearrangements are part of a large multi-protein complex that is associated with chromatin and drives leukemia through deregulation of transcriptional networks." (PMID 38049829, 2023). "Leukemia-associated translocations involving 11q23 lead to fusions of KMT2A to more than 90 different partner genes." (PMID 35269896, 2022). "The number of shared mutations between these leukemias suggests that the KMT2A rearrangement arose before gastrulation and specification of hematopoiesis." (PMID 35288693, 2022). "KMT2A-rearranged leukemia often present with CNS involvement and are associated with poor treatment outcome." (PMID 35294722, 2022). "KMT2A encodes for a histone methyltransferase involved in epigenetic regulation of blood cell development, and its deregulation is associated with leukemia initiation." (PMID 36140308, 2022). "This suggests an array of cells with individual RAS-pathway mutations and that KMT2A-r leukemia is more genetically heterogeneous than previously known." (PMID 36204688, 2022). "In clinical diagnostic and therapeutic terms, KMT2A-rearranged infant B-ALL is considered to be a B-precursor leukemia." (PMID 35288693, 2022). "This modification is catalyzed by disruptor of telomere silencing 1-like (DOT1L) and has been shown to be critical in leukemias bearing rearrangements of the gene encoding KMT2A for survival and maintenance of malignant potential." (PMID 34204821, 2021). "A common rearrangement in leukemia involves the chromosomal region containing the gene encoding for KMT2A." (PMID 34204821, 2021). "VTP50469 is a potent and specific inhibitor of the Menin/KMT2A interaction with demonstrated activity against KMT2A-fusion leukemia and NPM1-mutated leukemia, where it targets wild-type KMT2A." (PMID 33542482, 2021). "In 2016, the WHO identified the mixed-lineage leukemia (MLL) gene KMT2A (lysine (K)-specific methyltransferase 2A), encoded in the 11q23 chromosomal region." (PMID 33469688, 2021). "Efforts are made to find chemicals that can be used to treat leukemias caused by KMT2A rearrangements." (PMID 33302406, 2020). "KMT2 mutations resulting from the rearrangements of the KMT2A (MLL1) gene at 11q23 are associated with pediatric mixed-lineage leukemias, and recent studies demonstrate that KMT2 genes are frequently mutated in many types of human cancers." (PMID 33302406, 2020). "Chromosomal rearrangements of the lysine methyltransferase 2A (KMT2A), known also as mixed-lineage leukemia (MLL) gene, are associated with high-risk infant, pediatric, adult, and therapy-induced acute leukemia." (PMID 31253180, 2019). "In mixed lineage leukemia, chromosomal translocations between the gene encoding KMT2A/MLL1 and one of more than 80 partner genes have been detected." (PMID 29498679, 2018).
leukemia (continued). "A prominent example is offered by mixed lineage leukemia (MLL)-associated leukemia, which is characterized by chromosomal rearrangements involving the KMT2A/MLL gene." (PMID 28718414, 2017). "KMT2A is present in chr11q23 region that undergo frequent genomic rearrangements, and somatic mutations in KMT2A are associated with leukaemia." (PMID 28117658, 2016). "Taken together with these findings, our resultssuggest that increased sensitivity to TOP2 inhibitors caused by mutations or defectsof ATM pathways leads to KMT2A rearrangement, ultimately resultingin the development of infant leukemia." (PMID 26657054, 2015). "In this Review article we summarize our current understanding about the biology of pathogenic KMT2A‐complex function in cancer, specifically leukemia, and give a systematic overview of lessons learned from recent clinical and preclinical studies using Menin inhibitors." (PMID 39887730, 2026). "Moreover, non‐rearranged KMT2A‐complexes have been demonstrated to be crucial for disease development and maintenance in NPM1‐mutated and NUP98‐rearranged leukemia, expanding the spectrum of genetic disease subtypes that are dependent on KMT2A." (PMID 39887730, 2026). "Understanding their interplay with KMT2A fusion proteins not only provides new insights into leukemogenesis but also highlights promising opportunities for therapeutic intervention and precision medicine in this high-risk leukemia subtype." (PMID 41358901, 2025). "Menin functions as an obligate chromatin scaffold, anchoring KMT2A (MLL) fusion complexes to HOX loci in concert with LEDGF and the SEC/DOT1L machinery, sustaining a HOX/MEIS-high transcriptional state that defines KMT2A-rearranged leukemia and ∼30% of NPM1-mutated AML." (PMID 41347170, 2025). "Various KMT2A-associated malignancies, especially KMT2A-PTD and KMT2A-a leukemias, which exhibit unfavorable prognoses and require improved therapeutic options, may benefit from WT KMT2A inhibitors." (PMID 40361241, 2025). "Therefore, disrupting the menin‐KMT2A axis is a promising treatment approach for tackling leukemias driven by KMT2A rearrangements and NPM1 mutations." (PMID 39428967, 2024). "Moreover, KMT2A‐r leukemia is linked to profound epigenetic dysregulation, such as histone acetylation, histone methylation, and DNA methylation." (PMID 39428967, 2024). "Additionally, JNJ-75276617, targeting the menin–KMT2A interaction, exhibited promising preclinical activity in KMT2A-rearranged or NPM1-mutated leukemias." (PMID 38790937, 2024). "In addition, therapy-related leukemias that arise from exposure to topoisomerase II inhibitors are characterized by KMT2A rearrangements and are associated with treatment failure." (PMID 39179671, 2024). "KMT2A‐related cancers are strongly associated with large somatic chromosomal rearrangements with over 100 translocation partners creating fusion proteins linked to disease phenotypes of particularly aggressive adult and infantile leukemias." (PMID 36479909, 2023). "While KMT2A-PTD mutations are typically associated with poor prognosis, isolated KMT2A-PTD mutations are not sufficient to establish leukemic transformation of hematopoietic cells, highlighting the importance of cooperating genetic lesions, such as FLT3 mutations in KMT2A-rearranged leukemias." (PMID 35387132, 2022). "It is still under debate whether KMT2A fusions alone are sufficient to cause clinically overt leukemia." (PMID 34575904, 2021). "Interestingly, the Menin/KMT2A interaction has also been found to be required in other subtypes of leukemia such as those with NPM1c and C/EBPα mutations." (PMID 33542482, 2021). "Furthermore, GSEA revealed that a set of genes that we had previously found to be downregulated upon loss of Kmt2a in MN1-driven leukemia was enriched in Men1−/− versus Men1wt MN1-driven AML cells." (PMID 33542482, 2021).